ZNF664 (zinc finger protein 664)
Description:
May be involved in transcriptional regulation.
Synonyms: ZFOC1; ZNF176; DKFZp761B128
Tractability: PROTAC: UniProt records ubiquitination sites on it; ubiquitination databases record sites on it.
Gene: Protein-coding gene on chromosome 12 (123,971,745 to 124,015,445, forward strand). Ensembl gene ENSG00000179195.
Subcellular location: Nucleus
Subcellular location (Human Protein Atlas): Nucleoplasm
Pathways (Reactome):
Gene expression (Transcription): Generic Transcription Pathway
Gene Ontology:
Molecular function: protein binding; DNA-binding transcription factor activity, RNA polymerase II-specific; RNA polymerase II cis-regulatory region sequence-specific DNA binding
Biological process: regulation of DNA-templated transcription; regulation of transcription by RNA polymerase II
Cellular component: nucleus
Genetic constraint (gnomAD): Loss-of-function variants: 10 observed, 18.76 expected, observed/expected ratio (o/e) 0.53, 90% interval 0.33 to 0.9. The upper end of that interval is the gene's LOEUF score, 0.9, which puts it in group 3 of 6, group 1 being the genes least tolerant of losing a copy. Missense variants: 193 observed, 336.52 expected, observed/expected ratio (o/e) 0.57, 90% interval 0.51 to 0.65. Synonymous variants: 119 observed, 110.62 expected, observed/expected ratio (o/e) 1.08, 90% interval 0.93 to 1.25.
Homologues: Orthologues: dog ZNF664 (100% identical), macaque ZNF664 (100% identical), mouse Zfp664 (100% identical), pig ZNF664 (100% identical), rat Zfp664 (100% identical), guinea pig ZNF664 (78% identical), chimpanzee ZNF664 (77% identical), rabbit ZNF664 (71% identical), Drosophila melanogaster CG18476 (32% identical), Drosophila melanogaster CG10669 (30% identical). Paralogues in human: ZFP62 (53% identical), ZNF721 (51% identical), ZNF808 (51% identical), ZNF485 (30% identical), ZNF648 (27% identical).
Diseases named in the same sentence as ZNF664 in open-access papers:
ZNF664 is named in the same sentence as 16 diseases in open-access papers, as found by Europe PMC text mining. Sharing a sentence is not in itself a finding about the gene and the disease. The quoted sentences say what the papers report.
clubfoot (3 papers, 2020 to 2025). The most common congenital deformation of the foot, occurring in 1 of 1,000 live births. "Both SNPs are located at gene ZNF664 in chromosome 12, which was previously identified to be associated with clubfoot." (PMID 34568916, 2021).
metabolic syndrome (3 papers, 2012 to 2024). A cluster of metabolic risk factors for CARDIOVASCULAR DISEASES and TYPE 2 DIABETES MELLITUS. "Therefore, adiponectin risk alleles at ZNF664 and PEPD are of considerable interest since they impart deleterious changes on aspects of the metabolic syndrome (increased TC, TG, LDL-C and WHR and decreased HDL-C), but also act to decrease BMI and percent fat." (PMID 22479202, 2012).
cervical cancer (1 paper, 2022). A primary or metastatic malignant neoplasm involving the cervix. "Thus, FSCN1 negatively regulates four transcription factors (HLTF, HBP1, ZNF664, DDX17) and positively regulates ANGPTL4 (an angiogenic factor) and EPHA2 in both HeLa cells and cervical cancer tissues." (PMID 35178306, 2022). "The results showed that the expression of FSCN1 had a significant negative correlation (P < 0.05) with that of HLTF, HBP1, ZNF664, CTGF, DDX17, and KRT18 in cervical cancer tissues." (PMID 35178306, 2022).
Obesity (1 paper, 2021). Accumulation of substantial excess body fat. "A methylation site within ZNF664 was associated with higher HDL levels (β = 0.03, P = 9.4e−11), lower risk for obesity (β = −0.013, P = 3.5e−16) and CAD (β = −0.02, P = 2.5e−5)." (PMID 33574266, 2021).
ZNF664 also shares sentences with these, for which no sentence is quoted: breast carcinoma (1 paper); cancer (1); cervical tumor (1); coronary heart disease (1); metabolic disorders (1); osteoporosis (1); ovarian carcinoma (1); schizophrenia (1); Temple syndrome (1); tumor (1); type-2 diabetes (1); Williams syndrome (1).